YTHDF3 (YTH N6-methyladenosine RNA binding protein F3)
Description:
Specifically recognizes and binds N6-methyladenosine (m6A)- containing RNAs, and regulates their stability. M6A is a modification present at internal sites of mRNAs and some non-coding RNAs and plays a role in mRNA stability and processing. Acts as a regulator of mRNA stability by promoting degradation of m6A-containing mRNAs via interaction with the CCR4-NOT complex or PAN3. The YTHDF paralogs (YTHDF1, YTHDF2 and YTHDF3) share m6A-containing mRNAs targets and act redundantly to mediate mRNA degradation and cellular differentiation. Acts as a negative regulator of type I interferon response by down-regulating interferon-stimulated genes (ISGs) expression: acts by binding to FOXO3 mRNAs (By similarity). Binds to FOXO3 mRNAs independently of METTL3-mediated m6A modification (By similarity). Can also act as a regulator of mRNA stability in cooperation with YTHDF2 by binding to m6A-containing mRNA and promoting their degradation. Recognizes and binds m6A-containing circular RNAs (circRNAs); circRNAs are generated through back-splicing of pre-mRNAs, a non-canonical splicing process promoted by dsRNA structures across circularizing exons. Promotes formation of phase-separated membraneless compartments, such as P-bodies or stress granules, by undergoing liquid-liquid phase separation upon binding to mRNAs containing multiple m6A-modified residues: polymethylated mRNAs act as a multivalent scaffold for the binding of YTHDF proteins, juxtaposing their disordered regions and thereby leading to phase separation. The resulting mRNA-YTHDF complexes then partition into different endogenous phase-separated membraneless compartments, such as P-bodies, stress granules or neuronal RNA granules. May also recognize and bind N1-methyladenosine (m1A)-containing mRNAs: inhibits trophoblast invasion by binding to m1A-methylated transcripts of IGF1R, promoting their degradation. Has some antiviral activity against HIV-1 virus: incorporated into HIV-1 particles in a nucleocapsid-dependent manner and reduces viral infectivity in the next cycle of infection. May interfere with this early step of the viral life cycle by binding to N6-methyladenosine (m6A) modified sites on the HIV-1 RNA genome.
Synonyms: DF3; FLJ31657
Tractability: Small molecule: a structure with a bound ligand is known. PROTAC: ubiquitination databases record sites on it; its protein half-life has been measured.
Gene: Protein-coding gene on chromosome 8 (63,168,553 to 63,212,786, forward strand). Ensembl gene ENSG00000185728.
Subcellular location: Cytoplasm, cytosol; Cytoplasm, P-body; Cytoplasm, Stress granule
Gene Ontology:
Molecular function: N6-methyladenosine-containing RNA reader activity; protein binding; ribosome binding; RNA binding
Biological process: mRNA destabilization; organelle assembly; positive regulation of translation; positive regulation of translational initiation; regulation of mRNA stability; regulation of trophoblast cell migration; stress granule assembly; negative regulation of type I interferon-mediated signaling pathway
Cellular component: cytoplasm; cytoplasmic stress granule; P-body; cytosol
Genetic constraint (gnomAD): Loss-of-function variants: 7 observed, 48.3 expected, observed/expected ratio (o/e) 0.14, 90% interval 0.081 to 0.27. The upper end of that interval is the gene's LOEUF score, 0.27, which puts it in group 1 of 6, group 1 being the genes least tolerant of losing a copy. Missense variants: 516 observed, 722.94 expected, observed/expected ratio (o/e) 0.71, 90% interval 0.66 to 0.77. Synonymous variants: 270 observed, 247.42 expected, observed/expected ratio (o/e) 1.09, 90% interval 0.99 to 1.21.
Homologues: Orthologues: guinea pig YTHDF3 (99% identical), mouse Ythdf3 (99% identical), macaque YTHDF3 (97% identical), chimpanzee YTHDF3 (97% identical), pig YTHDF3 (97% identical), rabbit YTHDF3 (96% identical), rat Ythdf3 (96% identical), dog YTHDF3 (96% identical), tropical clawed frog ythdf3 (87% identical), zebrafish ythdf3 (84% identical), Drosophila melanogaster Ythdf (35% identical). Paralogues in human: YTHDF2 (68% identical), YTHDF1 (67% identical), YTHDC1 (17% identical).
Diseases named in the same sentence as YTHDF3 in open-access papers:
YTHDF3 is named in the same sentence as 115 diseases in open-access papers, as found by Europe PMC text mining. Sharing a sentence is not in itself a finding about the gene and the disease. The quoted sentences say what the papers report.
breast cancer (45 papers, 2020 to 2026). A primary or metastatic malignant neoplasm involving the breast. "To unravel the underlying mechanisms of YTHDF3 in breast cancer, we conducted a comprehensive analysis using bioinformatics tools and examined previously published meRIP-Seq and RIP-Seq data." (PMID 39372951, 2024). "Our analysis highlighted the significance of YTH N6-methyladenosine RNA-binding protein (YTHDF3) in constructing a risk model for breast cancer." (PMID 39372951, 2024). "In order to uncover the underlying mechanisms of YTHDF3 in breast cancer occurrence and development, we first analyzed conducted an analysis of RNA-seq datasets of YTHDF3 knockout cells and control cells available in the literature." (PMID 39372951, 2024). "In our research, we observed upregulation of the YTHDF3 gene in breast cancer, indicating an increased risk." (PMID 39372951, 2024). "It has been suggested that overexpression of the m6A reader YTHDF3 is clinically associated with brain metastasis in breast cancer patients." (PMID 38053093, 2023). "It has been shown that higher YTHDF1 and YTHDF3 expressions were correlated with a shorter survival in breast cancer (BC), and the importance of YTHDF3 as an independent risk factor for BC has been a topic of significant research." (PMID 33692959, 2021). "recently showed that YTHDF1 and YTHDF3 aberrations were associated with metastasis and predicted poor prognosis in breast cancer patients." (PMID 34804948, 2021). "The results in breast cancer patients showed that the relatively high expression of YTHDF3 and LRPPRC were remarkably associated with worse RFS, whereas relatively high expression of RBM15B, ZC3H13, and METTL16 had better RFS." (PMID 33362863, 2020). "YTHDF3 promotes the translation of m6A-modified mRNAs of breast cancer brain metastasis-associated genes (e.g., ST6GALNAC5, GJA1, and EGFR) by recruiting eIF3a and increasing the expression of the corresponding proteins, which ultimately affects the brain metastasis of breast cancer." (PMID 39440064, 2024). "Through its mechanism, YTHDF3 increases the translation of m6A-enriched transcripts associated with cerebral metastasis of breast cancer, such as ST6 N-Acetylgalactosaminide Alpha-2,6-Sialyltransferase 5 (ST6GALNAC5), Gap Junction Protein Alpha 1 (GJA1), and EGFR." (PMID 39342406, 2024). "The m6A regulators YTHDF1 and YTHDF3 were upregulated in breast cancer from TCGA and significantly associated with intrinsic subclasses and nodal metastasis, as well as poor prognosis of breast cancer patients." (PMID 36707507, 2023). "In addition, YTHDF3 has been confirmed to be closely associated with brain metastasis of breast cancer instead of lung and bone metastasis of breast cancer." (PMID 36324258, 2022). "In breast cancer (BC) brain metastasis, YTHDF3 enriches transcripts associated with metastasis and promotes the interaction between tumor cells and other cells in the tumor microenvironment, facilitating angiogenesis and metastasis." (PMID 39295872, 2024). "In this study, we elucidated that YTHDF3 regulates the glycolysis level, proliferation and migration of breast cancer through the mTOR-HIF1α-LDHA axis." (PMID 42036761, 2026). "Our results showed that YTHDF3 was highly expressed in breast cancer cells and clinical tissues, and YTHDF3 enhanced the proliferation and migration ability of breast cancer." (PMID 42036761, 2026). "In this study, we used bioinformatics to analyse the expression of YTHDF3 in breast cancer and verified it in clinical specimens." (PMID 42036761, 2026). "We aimed to elucidate the role of YTHDF3 in breast cancer development and provide evidence for improving the diagnosis and treatment of breast cancer." (PMID 42036761, 2026). "Interference of the YTHDF3 expression is a potential target for breast cancer treatment, which provides strong evidence for improving diagnosis and treatment methods." (PMID 42036761, 2026).
breast cancer (continued). "YTHDF3 interacts with solute carrier family 31 member 1 (SLC31A1) to co‐regulate citrate synthesis in breast cancer." (PMID 40923717, 2026). "Alternatively, YTHDF3 can promote brain metastasis and growth of breast cancer (BC) cells by preferentially translating m6A-rich transcripts such as ST6GALNAC5 and EGFR." (PMID 41446042, 2025). "The study found that YTHDF3 expression increased in patients with brain metastases from breast cancer, whereas its depletion impaired the formation of brain metastases and prolonged the survival of mice." (PMID 40356596, 2025). "YTHDF3 can promote breast cancer cell adhesion and extravasation across the brain endothelium by enhancing interactions between cancer cells and astrocytes, as well as promoting angiogenesis in the context of breast cancer brain metastasis." (PMID 40356596, 2025). "YTHDF3 augments cap-independent translation during breast cancer brain metastasis by promoting the interaction of eIF3a with the m6A residue located in the 5’ UTR of the YTHDF3 mRNA." (PMID 40356909, 2025). "Our analysis of multiple biomolecules revealed that fibroblast growth factor 2 (FGF2) is directly targeted by YTHDF3 in breast cancer cells." (PMID 39372951, 2024). "We initially observed that YTHDF3 expression was abnormally upregulated in breast cancer and played a crucial role in breast cancer cell growth and metastasis." (PMID 39372951, 2024). "Our data provide evidence that the m6A reader YTHDF3 plays a critical oncogenic role in the development of breast cancer." (PMID 39372951, 2024). "Collectively, these findings highlight the pivotal role of YTHDF3 in the proliferation, migration, and invasion of breast cancer cells, suggesting its potential as a pro-oncogenic factor in breast cancer progression." (PMID 39372951, 2024). "According to previous reports, the overexpression of YTHDF3 induces brain metastasis in breast cancer patients, which leads to a poor patient prognosis." (PMID 39440064, 2024). "YTHDF3 promotes the interaction of breast cancer cells with brain endothelial cells and astrocytes, blood–brain barrier extravasation, angiogenesis, and growth." (PMID 39006762, 2024). "We introduced point mutations W438A and W492A in the YTH domain of FLAG-tagged YTHDF3 (YTHDF3-OE-mut) and transfected breast cancer cells with constructs expressing either wild-type YTHDF3 (YTHDF3-OE-wt) or mutant YTHDF3 (YTHDF3-OE-mut)." (PMID 39372951, 2024). "Knockdown of YTHDF3 in breast cancer cells led to significant inhibition of cell self-renewal, migration, and invasion abilities in vitro." (PMID 39372951, 2024). "Previous studies have also emphasized the involvement of YTHDF3 in brain metastasis of breast cancer cells, as well as its significant role in the progression and metastasis of triple-negative breast cancer through the YTHDF3-ZEB1 axis." (PMID 39372951, 2024). "In summary, our research elucidates the critical role of YTHDF3 in breast cancer progression and unveils an intriguing m6A-dependent regulatory mechanism." (PMID 39372951, 2024). "The translation efficiency of ST6GALNAC5 mRNA was also tightly regulated by its m6A modification and read by the m6A reader YTHDF3 in brain-specific metastatic breast cancer cells." (PMID 37468844, 2023). "As previously commented, YHTDF1 and YTHDF3 are amplified and overexpressed in breast cancer, correlating with poor overall survival and nodal metastasis." (PMID 37369946, 2023). "In breast cancer brain metastasis, YTHDF3 overexpression due to increased copy number has been also described." (PMID 37369946, 2023). "Overexpression of YTHDF3 increases the invasive and angiogenic potential of cells in vitro and promotes breast cancer metastasis." (PMID 38053093, 2023). "In breast cancer, high expression of YTHDF1 and YTHDF3 is associated with gene copy number amplification and induces a poor prognosis." (PMID 36999016, 2023).
breast cancer (continued). "A recent study demonstrated that the N6‐methyladenosine reader YTHDF3 enhances the angiogenesis of breast cancer brain metastasis." (PMID 37830128, 2023). "Further experiments have shown that over expression of YTHDF3 is a key step in the brain metastasis of breast cancer." (PMID 35436972, 2022). "Compared with primary breast cancer, the expression of YTHDF3 was significantly increased in breast brain metastase, but there was no change in lung, bone, liver, spleen, lymph nodes and adrenal metastases." (PMID 35436972, 2022). "The regulators YTHDF1, YTHDF3 and KIAA1429 were found to be upregulated in breast cancer, and were associated with the metastasis of lymph nodes, breast cancer progression, and also were predictors of poor prognosis." (PMID 35721510, 2022). "We also utilized the Kaplan-Meier plotter website (KM plotter.com) to perform survival analysis for YTHDF3 as a biomarker of lung cancer, gastric cancer, breast cancer, and ovarian cancer." (PMID 36606187, 2022). "The results showed higher YTHDF3 protein expression levels in primary breast cancer, HCC, ovarian cancer, colon cancer, UCEC, and LUAD tissues compared with normal tissues (P < 0.001)." (PMID 36606187, 2022). "YTHDF3 gene amplification occurs frequently and leads to high expression levels in human breast cancer." (PMID 36606187, 2022). "In recent years, a study confirmed that YTHDF3 promotes breast cancer metastasis by promoting the translation of ST6GALNAC5, GJA1 and EGFR." (PMID 35197112, 2022). "With respect to TCGA, higher expression levels of YTHDF3, IGF2BP1 and KIAA1429 were associated with shorter OS of breast cancer patients in univariate analysis." (PMID 34141492, 2021). "YTHDF3 copy number gain is higher in breast cancer with brain metastases than in primary breast tumours." (PMID 34044876, 2021). "uncovered an essential role of YTHDF3 in regulating the interaction between breast cancer cells and brain microenvironment by upregulating key brain metastatic proteins, thereby facilitating brain metastasis." (PMID 35004283, 2021). "A univariate Cox regression model revealed the prognostic values of 15 m6A regulators in patients with breast cancer, and only YTHDF3 had prognostic significance." (PMID 34804948, 2021). "Both YTHDF1 and YTHDF3 overexpression correlated with poor overall survival in breast cancer patients (all P values < 0.05)." (PMID 34044876, 2021). "In the ONCOMINE and TCGA databases, we didn’t notice a considerable difference in the expression of RBM15B and YTHDF3 in breast cancer." (PMID 33362863, 2020). "However, the mechanism by which YTHDF3 regulates the occurrence and development of breast cancer is still imperfect." (PMID 42036761, 2026). "In addition, YTHDF3 knockdown breast cancer cell lines were used to determine the biological role of YTHDF3 in breast cancer through functional experiments such as CCK-8 assay, transwell assay, clonal proliferation and cell cycle assay." (PMID 42036761, 2026). "Finally, YTHDF3 knockout breast cancer cell lines were used to establish cell line-derived xenograft (CDX) mouse models to further confirm the biological function of YTHDF3 in breast cancer and the possible regulatory mechanism." (PMID 42036761, 2026). "Furthermore, the biological functions of YTHDF3 and its target genes in breast cancer cells were validated through CRISPR-Cas9 technology and rescue experiments." (PMID 39372951, 2024). "Notably, YTHDF3 displayed significant expression and correlation with various subtypes of breast cancer in the TCGA database." (PMID 39372951, 2024). "These conflicting observations further fuel our curiosity about whether YTHDF3 influences the malignant processes of breast cancer cells by regulating FGF2 expression." (PMID 39372951, 2024). "Furthermore, the wound healing assay revealed a notable decrease in the scratch healing ability of breast cancer cells after YTHDF3 knockdown." (PMID 39372951, 2024).